BDNF (brain derived neurotrophic factor)
Diseases named in the same sentence as BDNF in open-access papers (continued):
Sharing a sentence is not in itself a finding about the gene and the disease.
depression (continued). "We extend these findings and report a possible link between increased brain lactate concentrations, indicative of hypermetabolism, and decreased peripheral BDNF concentrations, a well-established marker for depression." (PMID 40308263, 2025). "It has even been proposed to evaluate plasma BDNF levels as a biomarker of depression, and ketamine, one of the most promising molecules as an antidepressant, would be able to modulate BDNF levels." (PMID 41373743, 2025). "Elevated fibrinogen levels were observed in participants with both anxiety and depression, while endocan and BDNF levels were lower in those with anxiety." (PMID 40491453, 2025). "Compared to healthy individuals, patients with depression typically exhibit lower serum levels of BDNF, which significantly increase following treatment with antidepressants." (PMID 40655932, 2025). "Anxiety and depressive disorders observed in rats after myocardial infarction were strongly correlated with decreased brain-derived neurotrophic factor (BDNF) levels in the hippocampus." (PMID 41235111, 2025). "This study examines the effects of probiotics on depression severity, brain‐derived neurotrophic factor (BDNF), adrenocorticotropic hormone (ACTH), and cortisol levels in MDD patients." (PMID 40177327, 2025). "BDNF levels in serum, cerebrospinal fluid, and brain tissue are widely used as biomarkers for cognitive impairment and depressive disorders." (PMID 40426650, 2025). "Peripheral brain-derived neurotrophic factor (BDNF) is negatively correlated with mood symptoms in depressive disorders." (PMID 40943216, 2025). "Different from what has been observed in depressive disorders, independence between peripheral BDNF levels and mood symptoms in CUD was observed." (PMID 40943216, 2025). "Some authors suggest that in most cases, poor sleep quality increases stress and, therefore, susceptibility to depressive disorders, and that there is a relationship between sleep, depression, and BDNF levels." (PMID 39829139, 2025). "In humans, some studies have revealed higher peripheral BDNF levels in cocaine users compared to control subjects and higher blood BDNF in subjects with CUD-induced depressive disorder." (PMID 40943216, 2025). "An example of direct signaling is the regulated expression of brain-derived neurotrophic factor (BDNF), a neuronal factor associated with depression, by short-chain fatty acids (SCFAs) produced in the gut." (PMID 38250995, 2024). "In these previous studies, the pathway of the protective effects of vitamin D against depression was seen in the involvement of BDNF." (PMID 39135986, 2024). "This consistency underscores BDNF's utility in quantifying depression severity and assessing treatment efficacy." (PMID 40226670, 2024). "Research has shown reduced BDNF levels in the brains of individuals who died by suicide, people with depression, and animals under stress, mirroring our findings." (PMID 39684342, 2024). "Recently, it was discovered that CREB/BDNF expression is essential for the pathophysiology of depression." (PMID 38315652, 2024). "This evidence suggests that acquired hypothyroidism can induce depression by reducing adult neurogenesis and BDNF expression in the hippocampus." (PMID 39100850, 2024). "BDNF plays a crucial role in synaptic activity and long-term synaptic memories, and changes in its levels can influence learning, memory, and depression-like behaviors." (PMID 39355088, 2024). "Several confounding factors are able to make changes in BDNF level in individuals such as socioeconomic status which can lead to escalating rate of depression, different type of mental disorders and administration of number of medicines including Analgesics." (PMID 38218833, 2024). "Studies have shown that inhibiting CREB signaling in the hippocampus disrupts the expression of genes including BDNF, thereby inducing depression-like behavior." (PMID 38377025, 2024).
depression (continued). "Numerous BDNF‐related studies have focused extensively on the relationship between the precursor of BDNF (pro‐BDNF) and mature BDNF (mBDNF) and depression." (PMID 39639753, 2024). "A reduction in BDNF impaired neurogenesis, resulting in the onset of major depressive disorder, and SCFAs exerted a beneficial effect on depression by recovering the brain’s BDNF level." (PMID 37755674, 2024). "Animal experiments found that 2.5% BEO inhaled for 14 days reduced the immobility time of FST and increased HIPP BDNF levels in depression‐like rats." (PMID 38553964, 2024). "Yoga has been shown to improve physical performance, reduce depression, increase blood serotonin levels, increase BDNF levels, and regulate pain perception pathways." (PMID 39182253, 2024). "In the present study, Empa administration restored hippocampal p-CREB (Ser133) expression and BDNF concentration in Res model of depression, and thus, affording comparable effects to those of Esc." (PMID 39158617, 2024). "It was indicated that mood and cognitive functions improved in elderly patients with various levels of depression who underwent cognitive training, which was accompanied by an increase in the serum concentration of BDNF." (PMID 38672112, 2024). "Although epigenetic alterations as well as changes in BDNF expression have been widely investigated as potential biomarkers in adult depression, there is a significant paucity of research on this subject in the youth population." (PMID 38542252, 2024). "In the context of stress-related mood disorders, such as depression and anxiety, environmental stress significantly affects BDNF expression in various brain regions." (PMID 39203753, 2024). "The neurotrophic growth factor brain‐derived neurotrophic factor (BDNF) plays a crucial role in various neurodegenerative and psychiatric diseases, such as Alzheimer's disease, schizophrenia and depression." (PMID 39105714, 2024). "Taken together, our findings suggest a potential role for hippocampal BDNF expression in modulating both anxiety and depression-like behaviors, underscoring the intricate involvement of BDNF in the neurobiology of mood regulation." (PMID 39766310, 2024). "BDNF plays an important role in the pathophysiology of many neurodegenerative disorders, depression, anxiety and other psychiatric disorders." (PMID 39005627, 2024). "5-HT, BDNF, IL-6, and NO are all closely related to depression and are vital indicators for judging the severity of depression." (PMID 39062817, 2024). "Collectively, these results demonstrate that enhancing BDNF expression within the LC or the dLS effectively and sufficiently rescues depression‐like behaviors in the Sus mice." (PMID 38155473, 2024). "Conjugated linoleic acid and fish oil both enhanced brain BDNF and synaptic protein expression in a depression paradigm involving lupus-prone MRL/lpr elderly mice." (PMID 39459643, 2024). "This is an unexpected result, as reduced expression of FNDC5/irisin, and BDNF has been observed in patients suffering from depression and in some animal models of depression." (PMID 38194217, 2024). "Elevating BDNF expression or activating TrkB receptors can promote neuronal growth and survival, ultimately easing symptoms for depression patients." (PMID 39113199, 2024). "Studies have shown significantly lower levels of BDNF protein and mRNA and reduced mRNA levels of its receptor TrkB in the brain of patients with depression compared with those in the brain of healthy individuals." (PMID 39654612, 2024). "Rael Cahn stated that there was a significant positive correlation between improvements in depression and increases in BDNF in individuals who practice yoga." (PMID 38907644, 2024). "Another potential connection between depression and neurocognitive disorders lies in the concentration and activity of neurotrophic factors, particularly brain-derived neurotrophic factor (BDNF)." (PMID 39767653, 2024).
depression (continued). "Taken together, our findings demonstrate the critical role of BDNF signaling in the LCTH‐dLSSST circuit in the pathogenesis of depression." (PMID 38155473, 2024). "Clinical data have also revealed epigenetic changes in the BDNF gene in adult male patients with anxiety and depression and increases in BDNF levels following treatment with fluoxetine, an antidepression drug." (PMID 38907644, 2024). "Lavender, in turn, affects the increase of BDNF, thanks to which the plasticity of synapses develops, which is disturbed in depression." (PMID 39717381, 2024). "For instance, SIT with an intensity of 80–100% VO2 max increases the BDNF level and improves depression and anxiety by crosstalk with PKA/Akt/CREB and MAPK/CREB pathways, especially when mediated by the estrogen receptors in the female hippocampus." (PMID 39194500, 2024). "Previous studies have demonstrated that asiaticoside improves depression-like behavior in mice by upregulating 5-HT and BDNF levels in the hippocampus." (PMID 39494347, 2024). "NF-κB signaling is a critical player in depression and stress-related depressive-like behaviors, presumably through a positive feedback loop involving BDNF and the BDNF/NFKB feedback loop in depression." (PMID 38256187, 2024). "Zn affects BDNF synthesis, and their supplementation in patients with depression increases serum BDNF levels." (PMID 39324118, 2024). "A transcriptome analysis showed that PAS840 upregulated the BDNF/VGF/NGFR pathway and increased neurotrophic nutrition to promote neurological function recovery and attenuate the risk of IS-induced depression." (PMID 39679371, 2024). "In conclusion, BDNF has emerged as a key factor in the pathophysiology of depression and the therapeutic effects of antidepressants, particularly ketamine and esketamine." (PMID 39684808, 2024). "For instance, if the patient also suffers from Chronic unpredictable mild stress-induced depression-like behaviors in rats will change the structure of the Lactobacillus casei by activating BDNF-TrkB." (PMID 38654189, 2024). "Omega-3 polyunsaturated fatty acids are important neurotransmitters, influencing depression by regulating 5-HT, dopamine, and brain-derived neurotrophic factor." (PMID 38404466, 2024). "Exogenous ALLO supplementation improves the depression- and anxiety-like behaviors in rats exposed to chronic stress and its beneficial effects are secondary to increased BDNF levels in the brain." (PMID 38743109, 2024). "Over-methylation of certain genes, such as BDNF, NR3C1, and SLC6A4, has been identified as a marker of increased susceptibility to depression." (PMID 39194576, 2024). "It has been demonstrated that insomnia and low sleep quality reduce the level of BDNF, which in turn is also altered in related affective disorders like depression." (PMID 38519465, 2024). "Substances that upregulate BDNF were shown to mitigate the effects of chronic stress-induced depression by ameliorating the HPA axis and the hippocampal glucocorticoid receptor (GR) dysfunctions as well as the 5-HT system." (PMID 38255289, 2024). "The well-studied brain-derived neurotrophic factor (BDNF) is recognized as a potential drug for major depression and bipolar disorder." (PMID 39408672, 2024). "Glucocorticoid levels increase OS, decrease antioxidant capacity, are neurotoxic, also associated with decreased levels of BDNF and DHEA leading to depression and adversely affecting HPG and thus negatively impact reproductive health." (PMID 38777848, 2024). "Supplementary β‐alanine increases brain BDNF, improves cognition, and mitigates symptoms of anxiety and depression." (PMID 37183394, 2024). "The second studied pathway, FNDC5/irisin/BDNF, which can be stimulated by PGC1α and physical activity, did not seem to play a significant role in disturbances occurring in the used model of depression." (PMID 38194217, 2024).
depression (continued). "In conclusion, NIBS appears to be a promising treatment for PSSD, showing improvements in sleep quality and structure, depression symptoms, and levels of brain-derived neurotrophic factor in PSSD patients." (PMID 39539650, 2024). "A growing body of research demonstrated that the CREB/BDNF signalling pathway participates in the development of nerve growth and plays important roles in psychiatric disorders, such as depression, anxiety, and bipolar disorder." (PMID 38372284, 2024). "Multiple meta-analyses and systematic reviews have shown that exercise interventions significantly elevate BDNF levels in patients with depression, highlighting its potential as a biomarker for the antidepressant effects of physical activity." (PMID 40226670, 2024). "There is a two-way relationship between depression and BDNF expression in the hippocampus and prefrontal cortex." (PMID 38408937, 2024). "Intervention with Akkermansia municiphila significantly improved depressive-like behavior in mice and rectified aberrations in depression-related molecular markers (corticosterone, dopamine, and BDNF)." (PMID 38891970, 2024). "Numerous studies as well as the meta-analysis show that depressed populations have lower serum and plasma levels of BDNF, which was considered a promising biomarker for depression." (PMID 38384936, 2024). "Chronic stress can lead to elevated levels of IL-6 and plasma cortisol, along with decreased levels of cAMP-responsive element-binding protein (CREB) and brain-derived neurotrophic factor (BDNF), similar to changes seen in depression and mood disorders." (PMID 39329889, 2024). "In a study, the administration of exogenous BDNF to the hippocampal region of rats exhibiting depression-like behavior induced by chronic unpredictable mild stress (CUMS) was observed to ameliorate depressive symptoms." (PMID 38377025, 2024). "The cyclic AMP (cAMP)/cAMP-response element binding protein (CREB)/BDNF pathway serves as an important antidepressant pathway, as well as a significant route and target for pharmacotherapy in depression." (PMID 38389919, 2024). "A recent study in a genetic model of depression even showed an inverse correlation between circulating and brain BDNF." (PMID 39568824, 2024). "Taken together, dysregulation of brain RAS triggers the development and progression of depression through the reduction of brain 5HT and expression of BDNF and the induction of mitochondrial dysfunction, oxidative stress, and neuroinflammation." (PMID 37953501, 2024). "Evidence further suggests that deficits in BDNF contribute to the pathogenesis of both depression and Alzheimer’s disease." (PMID 38582859, 2024). "Research has reported a decrease in BDNF levels in instances of depression, and clinical studies have shown that supplementation with probiotics can lower depressive symptoms." (PMID 38919504, 2024). "In fact, reduced hippocampal BDNF levels were observed in patients suffering from depression, and increased BDNF levels were observed following antidepressant treatments." (PMID 39766310, 2024). "Accordingly, reduced BDNF levels have been reported in the brains of patients with depression and schizophrenia." (PMID 39682677, 2024). "A meta-analysis has also shown that BDNF is strongly reduced in severe depression while increasing during antidepressant treatment, even in the absence of clinical remission." (PMID 38542503, 2024). "In summary, these studies confirm the existence of a tight correlation between the pathogenesis of depression and the miR-206/BDNF pathway." (PMID 39219169, 2024). "So far, clinical studies on BDNF promoter methylation in depression have only been performed on populations of adult patients." (PMID 38542252, 2024). "They proposed that BDNF is involved in synaptic plasticity and that this is important for the recovery from depression." (PMID 39125827, 2024).
depression (continued). "Compared to other neurotrophic factors, BDNF has garnered considerable attention in depression research due to its involvement in neuronal repair during depression remission." (PMID 38898454, 2024). "BDNF, a key neurotrophic factor, improves anxiety and depression by regulating the growth of nerve cells and synaptic plasticity." (PMID 39012662, 2024). "Psychological problems, depression, and other comorbidities, once present, can further affect BDNF levels through the hypothalamic-pituitary-adrenal (HPA) axis, which in turn affects the patient's prognosis and leads to a vicious circle." (PMID 38707889, 2024). "Another way to connect astrocyte function with neuroplasticity and depression is through the impact of certain astrocyte activation states on BDNF expression." (PMID 39650796, 2024). "Nevertheless, current knowledge on the relationship between BDNF and depression in adolescents is still inconsistent, with contrasting results among different studies." (PMID 38542252, 2024). "In this regard, a reduction in the concentration and expression of nocturnal melatonin, somatotropin, and brain-derived neurotrophic factor (BDNF) was found in major depression patients." (PMID 38541952, 2024). "Patients with depression have been shown to have a decreased expression of tyrosine receptor kinase B (TrkB) and peripheral BDNF, which contributes to symptoms such as fatigue and cognitive impairment." (PMID 39519618, 2024). "Studies have shown that BDNF and its receptor, tropomyosin receptor kinase B (TrkB), play a key role in the pathology of depression and the mechanism of antidepressant action." (PMID 39844852, 2024). "BDNF protein and mRNA can be found in most brain areas, including the ones important in the pathogenesis of depression, such as the olfactory bulb, cortex, hippocampus, forebrain, and hypothalamus." (PMID 39201362, 2024). "According to a study of depression patients, the level of BDNF decreased with increasing severity of the disease, and the more serious the condition, the lower the level of BDNF." (PMID 39539631, 2024). "Elevated cortisol levels lead to BDNF expression being suppressed, which results in neuronal death and depression." (PMID 39113199, 2024). "We explored the efficacy of RVG-BDNF-Exos in delivering BDNF to the brain, using a depression model." (PMID 41221079, 2024). "A substantial amount of clinical and experimental data suggests that BDNF is integral to the pathophysiology of depression." (PMID 39484160, 2024). "The findings in the study reveal that these engineered exosomes proficiently delivered BDNF to neurons, alleviating depression-like behavior induced by LPS and reducing neuroinflammation by modulating the BDNF-TrkB signaling pathway." (PMID 41221079, 2024). "Reduced circulating mature-BDNF levels and a diminished mature-BDNF/pro-BDNF ratio in individuals with depression and bipolar disorder prove to be more responsive biomarkers than a reduction in total BDNF levels." (PMID 38182767, 2024). "BDNF–TrkB signaling plays a vital role in depression, where BDNF and p-TrkB levels are significantly low." (PMID 38178196, 2024). "Decreased BDNF levels in the hippocampus and PFC of patients with depression are associated with reduced hippocampal volume, decreased neuronal proliferation in the CA3 region, and increased neuronal apoptosis in the dentate gyrus region." (PMID 39639753, 2024). "Reduced BDNF levels have been consistently observed in a spectrum of disorders, including Alzheimer's disease, Parkinson's disease, depression, and schizophrenia." (PMID 39568824, 2024). "At the same time, moderate intensity possesses a protective effect in reducing depression by impacting SNP rs6265 for BDNF secretion." (PMID 39194500, 2024). "For example, exaggerated RAS in experimental diabetic rats induces downregulation of the BDNF/TrkB axis, leading to depression." (PMID 37953501, 2024).